ALK (ALK receptor tyrosine kinase)
Diseases named in the same sentence as ALK in open-access papers (continued):
Sharing a sentence is not in itself a finding about the gene and the disease.
non-small cell lung carcinoma (continued). "Since then, ALK rearrangement, mutations, or amplification was discovered in a series of tumors including lymphoma, neuroblastoma, and non-small cell lung cancer (NSCLC)." (PMID 29455642, 2018). "On one side are diseases that have targetable, gene-specific mutations (e.g., ALK-rearranged non-small cell lung cancer) and on the other side are markedly heterogeneous diseases where only non-discriminatory therapies have effect." (PMID 28486497, 2017). "The expression of the echinoderm microtubule-associated protein-like 4 (EML4)-ALK fusion oncogene, which is caused by a small inversion within chromosome 2p, was found in non-small cell lung cancer (NSCLC)." (PMID 27144340, 2016). "In the past decade, the advancement on the treatment targeting mutated Epidermal Growth Factor Receptor (EGFR) and Anaplastic Lymphoma Kinase (ALK) have changed considerably the possibility of therapy for Non Small Cell Lung Cancer (NSCLC) patients." (PMID 26422230, 2015). "A novel fusion gene of echinoderm microtubule-associated protein-like 4 (EML4) and anaplastic lymphoma kinase (ALK) has been recently identified in non-small-cell lung cancers (NSCLCs)." (PMID 25706305, 2015). "Patients with non-small cell lung cancer (NSCLC) with echinoderm microtubule-associated protein-like 4 (EML4)-anaplastic lymphoma kinase (ALK) rearrangements generally respond to ALK inhibitors such as crizotinib." (PMID 25096400, 2014). "The understanding of the role of gene mutations (EGFR, K-RAS and MET), gene fusions (ALK) and rearrangements (ROS-1), has improved the management of non-small-cell lung cancer patients." (PMID 25149536, 2014). "Translocation of ALK was reported as the most common cause of genomic ALK aberration in many cancers, including anaplastic large-cell lymphomas, non-small cell lung cancer, diffuse large B-cell lymphoma, and inflammatory myofibroblastic tumor." (PMID 25193856, 2014). "For example, non-small-cell lung cancers (NSCLC) harboring gain-of-function mutations in the epidermal growth factor receptor (EGFR) gene or anaplastic lymphoma kinase (ALK) genes are now likely to be treated with first-line tyrosine kinase inhibitors." (PMID 28250367, 2014). "The translocations of the anaplastic lymphoma kinase (ALK) gene with the echinoderm microtubule-associated protein-like 4 (EML4) gene on chromosome 2p have been identified in non-small-cell lung cancers (NSCLCs) as oncogenic driver mutations." (PMID 25407901, 2014). "ALK rearrangement is associated with the pathogenesis of various malignancies, including anaplastic large-cell lymphoma, non-small cell lung cancer, and neuroblastoma." (PMID 24938355, 2014). "Anaplastic lymphoma kinase (ALK) gene rearrangement represents a molecular subgroup as ALK positive of non-small cell lung cancer (NSCLC) that is susceptible to ALK-targeted inhibitor crizotinib." (PMID 24667320, 2014). "Recently, a fusion protein of echinoderm microtubule associated protein like-4 (EML4) and anaplastic lymphoma kinase (ALK) has been found in non-small cell lung cancer (NSCLC) patients." (PMID 23254764, 2013). "Crizotinib (PF-2341066, an ALK-inhibitor) is an FDA-approved drug for treating non-small cell lung cancer patients with a mutation in ALK." (PMID 24163262, 2013). "In non-small cell lung cancer, epidermal growth factor receptor gene mutations and anaplastic lymphoma kinase (ALK) gene rearrangements have a major impact upon the level of response to treatment with specific tyrosine kinase inhibitors." (PMID 22825000, 2012). "Activating gene rearrangements of anaplastic lymphoma kinase (ALK) have been identified as driver mutations in non-small-cell lung cancer, inflammatory myofibroblastic tumors, and other cancers." (PMID 22034911, 2011). "Notably, all three cases with detailed genetic findings involved the EML4::ALK (V3) fusion type, which has been reported to be associated with poor prognosis of ALK-rearranged non-small cell lung cancer." (PMID 40224190, 2025).
non-small cell lung carcinoma (continued). "Crizotinib, a tyrosine kinase inhibitor (TKI) targeting ALK, MET and ROS1, was approved as the first-line drug for ALK-rearranged metastatic non-small cell lung cancer, as ALK rearrangement is known as “diamond mutation” and lead to high sensitivity to ALK TKIs." (PMID 37733896, 2024). "Crizotinib, a small-molecule tyrosine kinase inhibitor targeting ALK, MET and ROS1, is the first-line drug for ALK-positive metastatic non-small cell lung cancer and is associated with severe, sometimes fatal, cases of cardiac failure, which increases the risk of mortality." (PMID 37733896, 2024). "Crizotinib was the first ALK inhibitor approved for non-small cell lung cancer with ALK mutations." (PMID 37765276, 2023). "ALK has been linked to several malignancies, including non-small-cell lung cancer (NSCLC)." (PMID 35557858, 2022). "In 2016, the world’s first cancer diagnostic product based on exosome miRNAs body fluid biopsy, ExoDx Lung (ALK), was launched, which could detect EML4-ALK mutations in patients with non-small cell lung cancer in real time." (PMID 36678650, 2022). "Anaplastic lymphoma kinase (ALK) rearrangement has also been reported in non-small cell lung carcinomas, such as Echinoderm microtubule-associated protein-like 4-anaplastic lymphoma kinase (EML4-ALK) fusion identified in a lung adenocarcinoma metastasis to the thyroid." (PMID 35328664, 2022). "However, for advanced non-small cell lung cancers (NSCLCs) harboring driver mutations such as EGFR or ALK mutations, immunotherapy exhibited impaired response compared to corresponding targeted therapies." (PMID 36123526, 2022). "Indeed, several retrospective studies of patients with EGFR and or ALK mutation non-small cell lung cancer (NSCLC) treated with local ablative therapy and continued treatment with targeted therapy resulted in improved progression-free survival." (PMID 33757458, 2021). "A recent report identified that copy-number variations (CNVs) of PDGFRA might be implicated in the resistance of ALK-positive non-small cell lung cancer to targeted therapies." (PMID 32005261, 2020). "Immunotherapy is less effective in non-small cell lung cancer (NSCLC) with driver mutations in epidermal growth factor receptor (EGFR) or anaplastic lymphoma kinase (ALK) and some may extrapolate this trend to other driver mutations." (PMID 33269152, 2020). "Although targeted therapy has been successful in the treatment of cancers such as EGFR- or anaplastic lymphoma kinase (ALK)-mutated non-small-cell lung cancer or BRAFV600E-mutated melanoma, targeting these mutations has been largely ineffective in glioblastoma." (PMID 33396284, 2020). "Furthermore, both mutations have been described as acquired crizotinib resistance mutation in tumors driven by ALK fusion proteins, including non-small-cell lung carcinoma (NSCLC) and inflammatory myofibroblastic tumors." (PMID 31452835, 2019). "Furthermore, other ALK fusion proteins shall be discussed, such as echinoderm microtubule-associated protein-like 4 (EML4)-ALK which is implicated in non-small cell lung carcinoma (NSCLC)." (PMID 31366041, 2019). "ALK is a receptor tyrosine kinase, associated with many tumor types as diverse as anaplastic large cell lymphomas, inflammatory myofibroblastic tumors, breast and renal cell carcinomas, non-small cell lung cancer, neuroblastomas, and more." (PMID 30813562, 2019). "Non-small cell lung cancer (NSCLC) patients with epidermal growth factor receptor (EGFR) mutations or anaplastic lymphoma kinase (ALK) fusions show dramatic responses to specific tyrosine kinase inhibitors (TKIs); however, after 10–12 months, secondary mutations arise that confer resistance." (PMID 29764505, 2018). "Research has reported that two genes in particular (human epidermal growth factor receptor [EGFR] and anaplastic lymphoma kinase [ALK]) are associated with improvements in therapeutic efficiency in non-small cell lung cancer patients receiving targeted therapies." (PMID 28683775, 2017).
non-small cell lung carcinoma (continued). "Brain metastases, particularly in non-small cell lung cancer patients, are among the common causes of disease progression with brain metastasis frequency in ALK inhibitor naive patients ranging from about 25 to 40%, which is high in patients with history of chemotherapy." (PMID 27049722, 2016). "A fusion between the EML4 (echinoderm microtubule-associated protein-like) and ALK (anaplastic lymphoma kinase) genes was identified in non-small cell lung cancer (NSCLC) in 2007 and there has been rapid progress in applying this knowledge to the benefit of patients." (PMID 26755435, 2016). "Besides epidermal growth factor receptor (EGFR) mutation, the non-small cell lung cancer (NSCLC) of anaplastic lymphoma kinase (ALK) rearrangement becomes another important clinical subtype." (PMID 25676399, 2015). "ALK mutations have also been implicated in the pathogenesis of rhabdomyosarcoma, inflammatory myofibroblastic pseudo tumor, neuroblastoma and non-small cell lung Cancer." (PMID 25888090, 2015). "Moreover, non-small cell lung cancers can test positive for ALK and BRAF mutations, which is useful for targeting the ALK and BRAF gene alterations during the course of molecular treatment." (PMID 25951941, 2015). "The identification of epidermal growth factor receptor (EGFR) mutation and anaplastic lymphoma kinase (ALK) rearrangements has changed the treatment of non-small cell lung cancer, creating a personalized treatment era that is based on the appropriate molecular selection of patients." (PMID 25295096, 2014). "Moreover, ALK fusion proteins have been implicated in the pathogenesis of a subset of non-small cell lung carcinomas (ALK+ NSCLC) and inflammatory myofibroblastic tumours (ALK+ IMT)." (PMID 22681779, 2012). "Furthermore, two secondary mutations in the kinase domain of the fusion protein EML4-ALK were discovered in non-small-cell lung cancer in tumor cells isolated from a patient during the relapse phase of treatment with the ALK inhibitor PF-02341066." (PMID 22192458, 2011). "Additionally, to the rare occurrence of de novo small-cell lung cancers (SCLCs) in non-smokers (<2%), some SCLCs are believed to develop through the transformation of lung adenocarcinomas (LUADs), a type of non-small-cell lung cancer (NSCLC) that carries EGFR mutations or ALK alterations (~14%)." (PMID 39858036, 2025). "According to the information supplied by EVs diagnostic, ExoDx lung (ALK), which can be utilized to assist physicians in determining if patients are amenable to targeted therapy with ALK inhibitors, has 88% sensitivity and 100% specificity in identifying non-small cell lung cancer." (PMID 38333685, 2024). "Also, YAP1 regulates anaplastic lymphoma kinase (ALK) by inhibiting the anti-apoptotic factors MCL1 apoptosis regulator and Bcl-xL (B cell leukemia/lymphoma), which has clinical significance for molecular targeted therapy in non-small cell lung cancer with ALK-positive mutations." (PMID 34539895, 2021). "More recently, ALK rearrangements have been implicated in a variety of tumor types, notably non-small cell lung carcinoma (NSCLC), inflammatory myofibroblastic tumors (IMT), and renal cancer." (PMID 26062823, 2015). "SMARCA4-deficient non-small cell lung cancer (SMARCA4-dNSCLC) is an aggressive malignancy with poor prognosis, rarely harboring EGFR, ALK, or ROS1 alterations." (PMID 41684594, 2026). "In non-small cell lung cancer, anaplastic lymphoma kinase (ALK) gene rearrangements represent key oncogenic drivers, and ALK tyrosine kinase inhibitors such as crizotinib have significantly improved clinical outcomes." (PMID 41679471, 2026). "Mutations in EGFR, KRAS, and BRAF are common in non-small cell lung cancer (NSCLC), while ALK, ROS1, and RET rearrangements define distinct molecular subtypes." (PMID 41012430, 2025).
non-small cell lung carcinoma (continued). "Previous studies have reported that EGFR and ALK double mutations have been found in the minority of patients with non-small-cell lung cancer, in which patients with double mutations have shorter OS values than patients with EGFR or ALK single mutations." (PMID 40236629, 2025). "Examples include the BCR::ABL1 gene fusion in patients with CML and ALK fusions (e.g. EML4::ALK) in non-small-cell lung cancer." (PMID 41421967, 2025). "ALK rearrangements, particularly the EML4–ALK fusion, are well documented in non-small cell lung cancer." (PMID 41300979, 2025). "Supporting evidence of PETI, the EML4-ALK fusion gene which is a feature of many non-small cell lung cancers was simulated in HEK293T cells by applying pegRNAs targeting intronic regions of EML4 and ALK with RTTs homologous to the other locus." (PMID 39609594, 2025). "Targeted molecular treatments for advanced non-small cell lung cancer (NSCLC) have been revolutionized by the identification of oncogenic activation in specific tyrosine kinases, such as EGFR, ALK, and ROS1, using driver mutations as biomarkers." (PMID 39851952, 2025). "In non-small cell lung cancer (NSCLC), acquired Nrf2 hotspot mutations demonstrate functional synergy with secondary anaplastic lymphoma kinase (ALK) mutations, conferring therapeutic resistance to second-generation ALK inhibitors." (PMID 40868167, 2025). "Choosing the optimal first-line treatment for patients with advanced non-small cell lung cancer (NSCLC) with anaplastic lymphoma kinase (ALK) rearrangements can be challenging in daily practice." (PMID 40649750, 2025). "As an example, EGFR and anaplastic lymphoma kinase (ALK) targeted therapies have dramatically altered management of non-small cell lung cancer (NSCLC)." (PMID 40100294, 2025). "Later generations of ALK inhibitors, such as brigatinib, ceritinib, alectinib, and lorlatinib, have demonstrated significant efficacy in the treatment of non-small cell lung cancer, by substantially prolonging PFS and overcoming resistance mechanisms." (PMID 40227698, 2025). "The present retrospective study was thereby conducted to investigated the efficacy and safety of the BRICS sequential therapeutic regimen in PD-L1-negative metastatic non-small cell lung cancer patients harboring EGFR/ALK wild-type status." (PMID 40625736, 2025). "Inhibitors targeting EML4-ALK fusion proteins have emerged as crucial therapeutics for ALK-positive non-small cell lung cancer." (PMID 40584293, 2025). "Alectinib, a second-generation ALK inhibitor, is more effective and less toxic than crizotinib when used as the primary treatment for ALK-positive non-small-cell lung cancer." (PMID 40426987, 2025). "Targeted therapy has achieved significant success in the treatment of non-small cell lung cancer (NSCLC), particularly in patients harboring common oncogenic driver mutations such as EGFR, KRAS, and ALK rearrangement." (PMID 40246819, 2025). "The recently completed INSPIRE trial demonstrated that iruplinalkib improved progression-free survival and intracranial antitumor activity compared with crizotinib in patients with anaplastic lymphoma kinase (ALK) -positive non-small-cell lung cancer (NSCLC)." (PMID 41190033, 2025). "Anaplastic lymphoma kinase tyrosine kinase inhibitors (ALK-TKIs) have become first-line therapies for advanced non-small cell lung cancer (NSCLC) with ALK rearrangements." (PMID 40137538, 2025). "Wu et al31 found that Alectinib markedly improved disease-free survival rates in ALK-positive non-small cell lung cancer patients after surgery when used as an adjuvant, outperforming platinum-based chemotherapy." (PMID 41340257, 2025). "For example, testing an anaplastic lymphoma kinase (ALK) inhibitor in a small cohort of unselected patients with non-small cell lung cancer, where the prevalence of an ALK alteration is 3–5%, would almost certainly fail to detect a clinical signal." (PMID 40550567, 2025).
non-small cell lung carcinoma (continued). "Crizotinib, a small-molecule TKI targeting ALK, has shown strong clinical activity and successfully applied to non-small-cell lung cancer therapy with ALK rearrangements." (PMID 41179654, 2025). "Top 10 productive countries/regions and top 10 productive institutions related to ALK-TKI in the treatment of Non-small cell lung cancer." (PMID 40894217, 2025). "ALK (anaplastic lymphoma kinase) rearrangements represent the third most predominant driver oncogene in non-small cell lung cancer (NSCLC)." (PMID 40113795, 2025). "Translocations involving ALK result in a tyrosine kinase that remains constitutively active, as observed in other neoplasms such as lymphomas and non-small cell lung cancer." (PMID 40070616, 2025). "Of the patients with non-small cell lung cancer, 2 out of 27 had targeted mutations like EGFR (n = 1) or ALK (n = 1) mutations and 15 tumors were PD-L1 positive." (PMID 39651456, 2025). "MET mutations have become a significant mechanism of resistance to ALK inhibitors in ALK-rearranged non-small-cell lung cancer." (PMID 40422509, 2025). "Recently, an incidence of VTE greater than 30% has been described in patients with pancreatic cancer and in specific molecular subtypes of non-small cell lung cancer with ROS-1 and ALK rearrangement." (PMID 40359988, 2025). "The oncogenic potential of ALK is predominantly driven by genetic alterations, including fusion rearrangements, most notably the EML4-ALK fusion in non-small cell lung cancer, activating point mutations, and gene amplification." (PMID 41614760, 2025). "This case underscores the importance of molecular profiling in diagnosing metastatic tumors and confirms lorlatinib as a highly effective first-line therapy for ALK-positive non-small cell lung cancer with atypical metastases." (PMID 41261685, 2025). "ALK inhibitors are effective in the treatment of inflammatory myofibroblastic tumor, non-small-cell lung cancer with ALK rearrangement and ALK-positive ALCL, and represent a therapeutic option for ALK-positive LBCL." (PMID 40869163, 2025). "Non-small cell lung cancer (NSCLC) is the most common type of lung cancer, characterized by a complex spectrum of driver gene mutations, including EGFR mutations and ALK fusions." (PMID 41488666, 2025). "Non-small cell lung cancer (NSCLC) is frequently associated with mutations in receptor tyrosine kinases (RTKs), such as EGFR and ALK." (PMID 40833497, 2025). "Patients with PD-L1-negative, EGFR/ALK wild-type metastatic non-small cell lung cancer (NSCLC) exhibit limited responses to immune checkpoint inhibitors (ICIs)." (PMID 40625736, 2025). "The ALK/MET inhibitor crizotinib is a promising cancer therapy used primarily for the treatment of non-small cell lung cancer, and demonstrated cytotoxic effects on cervical cancer, ovarian cancer, and also chordoma cell." (PMID 41442054, 2025). "Other important driver mutations such as anaplastic lymphoma kinase (ALK) rearrangement has a reported prevalence of 2- 7 % and rearrangements of the ROS1 gene occurring in 1–2 % of non-small cell lung cancers (NSCLCs)." (PMID 40112503, 2025). "Here, we identified crizotinib, a clinically approved anti-cancer drug for anaplastic lymphoma kinase (ALK)-positive non-small-cell lung cancer, as a potent inducer of megakaryocyte maturation." (PMID 40813622, 2025). "The most significant progress has been observed in melanoma and certain subtypes of non-small cell lung cancer (NSCLC), such as those with EGFR mutations or ALK translocations." (PMID 41296115, 2025). "Somatic rearrangements of the anaplastic lymphoma kinase (ALK) create common oncogenic fusions that lead to activation of different pathways in non-small cell lung cancer." (PMID 40869806, 2025). "As a result of constitutive activation of the ALK kinase, ALK-positive non-small-cell lung cancer (NSCLC) exhibits dysregulated cellular proliferation and survival through downstream signaling pathways." (PMID 40422509, 2025).